CPEB4 (cytoplasmic polyadenylation element binding protein 4)
Diseases named in the same sentence as CPEB4 in open-access papers (continued):
Sharing a sentence is not in itself a finding about the gene and the disease.
colorectal cancer (5 papers, 2016 to 2024). A primary or metastatic malignant neoplasm that affects the colon or rectum. "It has been reported that colorectal cancer tissues express high levels of CPEB4 and that high mRNA level is associated with advanced tumor stage, lymph node metastasis, distant metastasis and poor prognosis in patients with colorectal cancer." (PMID 33237662, 2021). "In one of the studies, high CPEB4 expression was correlated with advanced tumor stage, lymph node metastasis, distant metastasis, and poor prognosis in patients with colorectal cancers." (PMID 39408697, 2024). "There is a study that showed an increase in CPEB4 protein levels in colorectal cancer (CRC) patient samples using a Western blot analysis." (PMID 39408697, 2024). "In the same study, high CPEB4 expression was correlated with advanced tumor stage, lymph node metastasis, distant metastasis, and poor prognosis in patients with colorectal cancers." (PMID 39408697, 2024). "It has also been shown that CPEB4 is highly expressed in the peripheral blood of colorectal cancer patients as well." (PMID 39408697, 2024). "CPEB4 is involved in the regulation of intestinal inflammation resolution and colorectal cancer development." (PMID 39408697, 2024). "Similar to this study, in our study, CPEB4 mRNA level increased significantly in the peripheral blood of patients with colorectal cancer." (PMID 33237662, 2021). "The mRNA level of the CPEB4 gene was significantly downregulated in colorectal tumor tissues and was upregulated in the peripheral blood of colorectal cancer patients relative to the controls (P < 0.05)." (PMID 33237662, 2021). "When evaluated comparatively in terms of stages, the increase in the mRNA level of CPEB4 gene was found to be statistically significant in the peripheral blood samples of cases in colorectal cancer stages I and II." (PMID 33237662, 2021). "It has been suggested that CPEB4 is important in tumor invasion and metastasis processes, and high expression level is an indicator for poor outcome in colorectal cancer patients." (PMID 33237662, 2021). "The study concluded that TRIP13 and CPEB4 mRNA up-regulation in the peripheral blood of patients with colorectal cancer might be a potential target for an early-stage test of colorectal cancer." (PMID 36553654, 2022). "This suggests that the increase in CPEB4 mRNA level in peripheral blood since the early stages of colorectal cancer may be a potential biomarker for colorectal cancer." (PMID 33237662, 2021). "This suggests that CPEB4 gene expression in peripheral blood from the early stages of colorectal cancer may be an indicator for colorectal cancer." (PMID 33237662, 2021). "The results reported in this study appears to suggest that the increase in TRIP13 and CPEB4 mRNA levels in peripheral blood samples of colorectal cancer cases may be a potential biomarker in early stage diagnosis of colorectal cancer." (PMID 33237662, 2021). "TRIP13 and CPEB4 mRNA up regulation in the peripheral blood of patients with colorectal cancer may be a potential target for early stage diagnosis." (PMID 33237662, 2021). "It is thought that CPEB4 is over-expressed in a wide variety of tumors, including colorectal cancer, skin cancer and kidney cancer, and high expression of CPEB4 may also be effective in tumor development." (PMID 33237662, 2021). "In addition, CPEB4 has also been reported to be highly expressed in the peripheral blood of cases with colorectal cancer." (PMID 33237662, 2021). "The presence of the CPEB4/DUSP6 combination is a prerequisite for the significance of MMD, which supports the reported five-gene model for colorectal cancer." (PMID 36672653, 2023). "The real-time RT-PCR technique was recently applied to measure expression levels of CPEB4, APC, TRIP13, EIF2S3, EIF4A1, IFNg, PIK3CA, and CTNNB1 genes in tumors and peripheral blood samples of colorectal cancer patients in stages I–IV of the disease." (PMID 36553654, 2022).
colorectal cancer (continued). "The mRNA levels of CPEB4, APC, TRIP13, EIF2S3, EIF4A1, IFNg, PIK3CA and CTNNB1 genes expressed in colorectal cancer tissue specimens, colorectal cancer blood samples, normal colon tissues and blood samples were analysed." (PMID 33237662, 2021). "The aim of the study is to assess expression levels of CPEB4, APC, TRIP13, EIF2S3, EIF4A1, IFNg, PIK3CA and CTNNB1 genes in tumors and peripheral bloods of colorectal cancer patients in stages I–IV." (PMID 33237662, 2021).
osteosarcoma (5 papers, 2016 to 2024). A usually aggressive malignant bone-forming mesenchymal neoplasm, predominantly affecting adolescents and young adults. "To further analyze the contribution of p38α signaling to Cpeb4 mRNA stability, we used human osteosarcoma (U2OS) cells expressing the p38α MAPK activator MKK6 under the control of the TET-ON promoter." (PMID 35442882, 2022). "In osteosarcoma (OS), lncRNA RP11-361F15.2 is positively related to cytoplasmic polyadenylation element binding protein 4 (CPEB4) and negatively associated with miR-30c-5p." (PMID 36263199, 2022). "lncRNA RP11-361F15.2 is highly expressed in osteosarcoma (OS) tissues and correlated with cytoplasmic polyadenylation element binding protein 4 (CPEB4)." (PMID 33522932, 2021). "Supernatants from activated RAW264.7 macrophages overexpressing CPEB4 increased U2OS and MG-63 cell invasion and migration, highlighting the role of macrophage-derived CPEB4 in human osteosarcoma tumorigenesis." (PMID 39062974, 2024).
esophageal cancer (3 papers, 2021 to 2023). A primary or metastatic malignant neoplasm involving the esophagus. "CircRNA-DOPEY2 was found to enhance chemosensitivity of esophageal cancer cells by inhibiting cytoplasmic polyadenylation element binding protein 4 (CPEB4)-mediated translation of MCL1 (encoding myeloid cell leukemia 1)." (PMID 36609391, 2023).
liver cancer (3 papers, 2012 to 2021). An epithelial or non-epithelial malignant neoplasm that arises from the liver. "In vitro studies on liver cancer cells such as HepG2 revealed that CPEB4 knock-out promotes colony formation, and CPEB4 knock-down accelerates growth in xenograft mice." (PMID 34912244, 2021). "Although proliferation of hepatocytes appeared normal in CPEB4-knockout (KO) mice after partial hepatectomy, knockdown (KD) of CPEB4 in HepG2 liver cancer cells promoted colony formation in vitro." (PMID 27158894, 2016). "Similarly, in the GSE9843 dataset, significantly decreased CPEB4 mRNA level was associated with carcinogenic progression of HCC, defined by the Barcelona Clinic Liver Cancer (bclc) staging system." (PMID 27158894, 2016). "Downregulation of CPEB4 in liver cancers appears to advance HCC progression only at a late stage." (PMID 27158894, 2016). "Moreover, a decrease in CPEB4 expression mediated miR-550a-induced liver cancer cell migration and invasion." (PMID 23145039, 2012). "Therefore, we evaluated the expression of CPEB4 mRNA in various liver cancer cell lines." (PMID 23145039, 2012).
lung carcinoma (3 papers, 2016 to 2022). "In addition, five of the genes that we identified in this study, CPEB4, DUSP6, NF1, RNF4, and STAT2, were previously proposed as prognostic markers for NSCLC, whereas changes in the expression of MCM4 and WEE1 were associated with lung cancer development." (PMID 27418131, 2016).
neuroblastoma (3 papers, 2012 to 2020). Neuroblastoma (NB) is the most common solid, extracranial childhood tumor. "In the more aggressive neuroblastoma clinical groupings, RBPs with reported roles in neuronal function had less abundance (e.g., CPEB4), perhaps indicating a loss of the peripheral neuronal cell identity and function." (PMID 32707690, 2020). "In pancreatic ductal cancer and neuroblastoma, the expression of CPEB4 is upregulated, driving the growth and invasion of cancer cells." (PMID 23145039, 2012). "To investigate the cellular function of CPEB4 exon 1 LCD, we expressed a GFP tagged version of this 375 amino acid polypeptide as well as the C-term region (residues 376-712) and the full-length (FL) CPEB4 protein in N2a mouse neuroblastoma cells or 293T cells." (PMID 27381259, 2016). "CPEB4 was found to be upregulated in pancreatic ductal cancer and neuroblastoma." (PMID 23145039, 2012).
non-small cell lung carcinoma (3 papers, 2016 to 2021). A group of at least three distinct histological types of lung cancer, including non-small cell squamous cell carcinoma, adenocarcinoma, and large cell carcinoma. "We cannot comment on the study about CPEB4 expression in non-small cell lung cancer because many figures in this paper were replicated from the HCC study." (PMID 27158894, 2016). "Silencing of CPEB4 prevents cell invasion and migration in non-small cell lung cancer." (PMID 31335867, 2019).
prostate carcinoma (3 papers, 2019 to 2024). A carcinoma that arises from epithelial cells of the prostate gland. "Our study verified the tumor suppressor function of CPEB4 gene which was up-regulated by curcumin treatment after 48 h in prostate cancer cells." (PMID 31581661, 2019). "However, similar to our study, Xu and Liu reported that CPEB4’s mRNA level decreased compared to control in prostate cancer and adjacent tissues." (PMID 33237662, 2021).
Sepsis (3 papers, 2022 to 2023). Sepsis is defined as life-threatening organ dysfunction caused by a dysregulated host response to infection. "Accordingly, we found that CPEB4 was overexpressed in patients with sepsis, while myeloid-specific Cpeb4MKO mice with LPS-induced septic shock had lower survival rates and a more exacerbated inflammation than WT mice." (PMID 35442882, 2022). "Accordingly, CPEB4 depletion in macrophages impairs inflammation resolution in an LPS-induced sepsis model." (PMID 35442882, 2022). "The peripheral blood of sepsis patients displays an increased number of monocytes/macrophages, which are one of the immune cell populations that express higher Cpeb4 mRNA levels." (PMID 35442882, 2022). "CPEB4 downregulation in myeloid cells increases sepsis-induced mortality." (PMID 35442882, 2022). "Moreover, deconvolution analysis suggested that myeloid cells expressed higher levels of Cpeb4 mRNA during sepsis." (PMID 35442882, 2022). "Group B Strep sepsis was significantly associated with multiple cell clusters, including C8_DC, C9_STOM, C10_ULK1, C12_mix, C13_UBE2Z, and C16_B, and its signature genes, including CKAP4, CPEB4, TSPO, and TXN, were significantly upregulated in multiple relevant clusters." (PMID 37919720, 2023).
bladder cancer (2 papers, 2016 to 2022). "Shu YJ found that miR-29C-5p directly acted on CPEB4 and inhibited the MAPK signaling pathway to inhibit the proliferation and metastasis of bladder cancer." (PMID 35113040, 2022).
endometrial cancer (2 papers, 2022 to 2023). Primary or metastatic malignant neoplasm involving the endometrium (mucous membrane that lines the endometrial cavity). "CircESRP1 served as an oncogenic circRNA promotes the proliferation and metastasis of endometrial cancer cells through the miR-874-3p/CPEB4 axis." (PMID 37384727, 2023). "CircESRP1 can interact with miR-874-3p to regulate EMT in endometrial cancer via the miR-874-3p/CPEB4 axis." (PMID 35317822, 2022).
head and neck squamous cell carcinoma (2 papers, 2019 to 2025). A squamous cell carcinoma that arises from any of the following anatomic sites: lip and oral cavity, nasal cavity, paranasal sinuses, pharynx, larynx, and salivary glands. "This study aims to investigate the role of CPEB4 in head and neck squamous cell carcinoma (HNSCC), particularly focusing on nasopharyngeal carcinoma." (PMID 40084246, 2025).
liver disease (2 papers, 2021 to 2023). "CPEB4, for instance, is highly expressed in the liver and its essential role in the stress response during liver diseases has been recently reviewed." (PMID 34944111, 2021). "Furthermore, silencing CPEB4 in knockout mice in which liver disease has been induced prevents HSC activation and liver fibrosis." (PMID 34944111, 2021).
adenoma (1 paper, 2024). A neoplasm arising from the epithelium. "For the validation of some key genes identified in adenoma (IL6ST, GLI3) and carcinoma (MAPK8IP2, CPEB4) patients, survival analysis was completed by using the Kaplan–Meier Plotter." (PMID 39408697, 2024).
cardiac hypertrophy (1 paper, 2023). "Indeed, key components of the cytoplasmic polyadenylation complex, such as PABPC1 and CPEB4, are involved in cardiac hypertrophy." (PMID 37569379, 2023).
Cirrhosis (1 paper, 2012). A chronic disorder of the liver in which liver tissue becomes scarred and is partially replaced by regenerative nodules and fibrotic tissue resulting in loss of liver function. "CPEB4 expression was high (scored 3 or 4) in all 10 normal liver samples and in most of the cirrhosis samples and noncancerous cases." (PMID 23145039, 2012).
Cognitive impairment (1 paper, 2025). Abnormal cognition is characterized by deficits in thinking, reasoning, or remembering. "This reasoning is consistent with the involvement of the cytoplasmic polyadenylation element-binding protein 4 (Cpeb4) in the gene networks that are related to cognitive impairment, learning/memory, METH dependence, and delusional and neurological disorder." (PMID 40141377, 2025). "This impact of CPEB4 might explain, in part, the results of the IPA that revealed the potential involvement of CPEB4 in transcription, cognitive impairment, learning/memory, addictive behavior, METH dependence, and delusional and neurological disorder." (PMID 40141377, 2025).
colon cancer (1 paper, 2024). "Studies indicate that the suppression of CPEB4 expression can enhance apoptosis and decrease cellular proliferation in colon cancer cells." (PMID 39408697, 2024).
colorectal tumor (1 paper, 2021). "In our study, while the mRNA level of the CPEB4 gene was significantly decreased in all colorectal tumor tissues of the cases, it was observed that it is increased significantly in peripheral blood samples." (PMID 33237662, 2021). "In our study, CPEB4 mRNA level was significantly decreased in all colorectal tumor tissues." (PMID 33237662, 2021).
Crohn disease (1 paper, 2021). A gastrointestinal disorder characterized by chronic inflammation involving all layers of the intestinal wall, noncaseating granulomas affecting the intestinal wall and regional lymph nodes, and transmural fibrosis. "GWAS analysis has also implicated CPEB4 as being associated with Crohn’s disease." (PMID 34360971, 2021).
cutaneous T-cell lymphoma (1 paper, 2022). "First, we tested if CPEB4 expression is enhanced by HDAC inhibitors in general, using the pan-HDAC inhibitor Trichostatin A (TSA) and the structurally related suberoylanilide hydroxamic acid (SAHA), an FDA-approved HDAC inhibitor used for the treatment of refractory cutaneous T-cell lymphoma." (PMID 36096941, 2022).
esophageal squamous cell carcinoma (1 paper, 2022). Esophageal squamous cell carcinoma (ESCC) is a type of esophageal carcinoma (EC) that can affect any part of the esophagus, but is usually located in the upper or middle third. "cDOPEY2 serves as a protein scaffold to potentiate the interaction between the E3 ligase TRIM25 and cytoplasmic polyadenylation element binding protein (CPEB4), thereby promoting the ubiquitination and degradation of CPEB4 in esophageal squamous cell carcinoma." (PMID 36506086, 2022).
heart failure (1 paper, 2024). Inability of the heart to pump blood at an adequate rate to meet tissue metabolic requirements. "The reactivation of fetal-specific RBPs and the dynamic regulation of Cytoplasmic Polyadenylation Element-Binding Protein 4 (Cpeb4) are critical in heart failure, driving pathological cardiac growth and remodeling through targeted mRNA interactions." (PMID 39334823, 2024).
Hepatic steatosis (1 paper, 2017). Steatosis is a term used to denote lipid accumulation within hepatocytes. "Moreover, circadian control of cytoplasmic polyadenylation element binding-protein 4 (CPEB4) regulates a translational response that counteracts hepatic steatosis under ER stress." (PMID 29283886, 2017).
invasive ductal breast carcinoma (1 paper, 2019). The most common type of invasive breast carcinoma, accounting for approximately 70% of breast carcinomas. "High CPEB4 expression can serve as a prognostic factor in invasive ductal breast carcinoma." (PMID 31335867, 2019).
low grade glioma (1 paper, 2019). A grade I or grade II glioma arising from the central nervous system. "Some studies have shown decreased RNF43 expression correlated with poor prognosis in GBM and low grade glioma (LGG) patients, while high expression of CPEB4 was associated with shorter OS rates." (PMID 31692451, 2019).
memory impairment (1 paper, 2021). "CPEB4 is expressed at a high level in neurons of the brain and spinal cord of mice, although CPEB4 knockout mice develop normally and do not have memory impairments." (PMID 33789753, 2021).
metastatic cancers (1 paper, 2021). A carcinoma which has spread from the original site of growth to another anatomic site. "CPEB4 was an oncogenic gene that was up-regulated in a variety of tumors, and it was considered a potential marker for defining metastatic cancers." (PMID 33106913, 2021).